CPA3 (carboxypeptidase A3)
Diseases named in the same sentence as CPA3 in open-access papers (continued):
Sharing a sentence is not in itself a finding about the gene and the disease.
depression (1 paper, 2026). "Consistently, the mRNA levels of mast cell‐specific proteases, such as Chymase 1 (CMA1), Carboxypeptidase A 3 (CPA3), and Tryptase Beta 2 (TPSB2) were also upregulated in the brain from depression model mice." (PMID 41556446, 2026). "Similarly, the mast cell‐specific proteases (CMA1, CPA3, and TPSB2) that were increased in depression model mice were down‐regulated by DSCG treatment as well." (PMID 41556446, 2026).
glucocorticoid deficiency (1 paper, 2013). "Mast cells from Hsd11b1−/− mice have a phenotype consistent with relative glucocorticoid deficiency, including reduced expression of glucocorticoid-sensitive mast cell-specific carboxypeptidase A3, suggesting 11β-HSD1-mediated glucocorticoid amplification tonically suppresses mast cell responses." (PMID 23349944, 2013).
Granuloma (1 paper, 2025). A compact, organized collection of mature mononuclear phagocytes, which may be but is not necessarily accompanied by accessory features such as necrosis. "A diverse array of innate immune cells, including mast cells (MC) (cluster 20: HDC, CPA3, KIT), dendritic cells (DC) (cluster 23: CLNK, WDFY4, FLT3), neutrophils (FCGR3B, FFAR2, CSF3R), and macrophages (CD68, CD163, C1QA/B/C), was also present in these granulomas." (PMID 40772762, 2025).
liver cancer (1 paper, 2021). An epithelial or non-epithelial malignant neoplasm that arises from the liver. "CPA3 is a kind of metallo-carboxypeptidase that modulates inflammation, fibrosis, and stem cell niche formation in liver cancer, whose overexpression might associate with worse grades, stages, and prognosis of patients." (PMID 33878734, 2021).
lung carcinoma (1 paper, 2022). "Previous studies, all of which highlighted CPA3's importance in lung cancer, supported our conclusion." (PMID 35184748, 2022). "This indicated that CPA3 played a key role in lung tumors, and the combination of CPA3 with other genes could accurately predict the prognosis of patients with lung cancer." (PMID 35184748, 2022).
lung disease (1 paper, 2022). "The capacity of CPA3 to counteract these mediators would likely be beneficial in lung disease, like the protective actions of CPA3 demonstrated in animal models." (PMID 35983043, 2022). "Similar to our recent study on non-diseased lungs, the present study shows that also in advanced lung disease, mast cells may have high mRNA expression while displaying a seemingly surprising paucity of granule-stored CPA3 protein." (PMID 35983043, 2022). "However, the dynamics and spatial distribution of mast cell CPA3 expression in lung diseases remain unknown." (PMID 35983043, 2022).
Marfan syndrome (1 paper, 2024). A disorder of the connective tissue. "Analysis of the skin MC population in children with Marfan syndrome revealed a considerably increased number of intra-organic populations with the preservation of the specific Tryptase+Chymase+CPA3+ protease profile typical of the skin." (PMID 39273142, 2024).
melanoma of the skin (1 paper, 2022). "In this study, we performed multiple immunolabeling of tryptase, chymase, and carboxypeptidase A3 in patients with melanoma of the skin." (PMID 36012196, 2022).
metastatic disease (1 paper, 2022). "By establishing more specific cut-off values that predict true metastatic disease using RT-qPCR for CPA3 and tryptase, a better clinical correlation would be expected." (PMID 35237679, 2022). "Less than 5% (1/21) of HN3 nodes had an mRNA expression level of CPA3 and tryptase below the cut-off values, and metastatic disease would have been undetected by either molecular test." (PMID 35237679, 2022). "At 95% sensitivity, analysis of expression of CPA3 and tryptase RNA levels in HN2 nodes identified 8/20 (40%) and 2/20 (10%) of these nodes, respectively, as harboring metastatic disease." (PMID 35237679, 2022).
oral squamous cell carcinoma (1 paper, 2018). "For CPA3 (carboxypeptidase A3), it has been identified in a molecular signature of eleven genes for extracapsular spread in oral squamous cell carcinoma." (PMID 29681787, 2018).
osteoarthritis (1 paper, 2019). A noninflammatory degenerative joint disease occurring chiefly in older persons, characterized by degeneration of the articular cartilage, hypertrophy of bone at the margins and changes in the synovial membrane. "In the Cpa3-Cre;Mcl-1fl/fl mice that developed osteoarthritis, we observed peri-articular tryptase-positive mast cells suggesting that incomplete mast cell deficiency contributed to their development of osteoarthritis." (PMID 31084709, 2019). "To ascertain whether the reduction in osteoarthritis-related pathology in KitW-sh/W-sh and Cpa3-Cre;Mcl-1fl/fl mice was in fact due to the absence of mast cells, we engrafted bone marrow-derived mast cells into KitW-sh/W-sh and Cpa3-Cre;Mcl-1fl/fl mice to generate mast cell-sufficient mice." (PMID 31084709, 2019).
pneumonia (1 paper, 2024). An acute, acute and chronic, or chronic inflammation focally or diffusely affecting the lung parenchyma, caused by an infection in one or both of the lungs (by bacteria, viruses, fungi, or mycoplasma.). "Altogether, these findings show that during SARS-CoV-2 infection, there is an increase in MCs in the lungs, mainly CPA3+ MCs, and these cells are activated and degranulated, which was associated with pneumonia and tissue damage." (PMID 39596322, 2024). "Our findings demonstrate that during severe cases of SARS-CoV-2 infection, there is an increased amount of CPA3+ MCs in areas with pneumonia, around thrombotic blood vessels, and in fibrotic tissue." (PMID 39596322, 2024).
Pruritus (1 paper, 2020). Pruritus is an itch or a sensation that makes a person want to scratch. "This suggests that CPA3 has an important role in protection against exogenously administered ET-1 with regard to pruritus." (PMID 32321525, 2020).
tumor (30 papers, 2017 to 2026). "This study is the first to analyse MCs associated with an FGF23-producing tumour, including spatial phenotyping of specific proteases, tryptase, chymase, and carboxypeptidase A3." (PMID 40981193, 2025). "In our study, comprehensive qPCR analysis of tumor samples revealed significant differences between the experimental groups regarding the MC-associated markers Cpa3, Il-3 as well as the MC-proteases (Mcpt1, 2, 4, 5, 6, 7)." (PMID 37686555, 2023). "Accordingly tumor growth of gp130FF mice was susceptible to the highly mast cell-selective cellular deficiency in gp130FF; Cpa3-Cre; Mcl1fl/fl mice, or to cromolyn-dependent inhibition of mast cell degranulation." (PMID 31227713, 2019). "Higher IHC staining scores of all markers were significantly associated with worse predicted tumour response, except for CPA3 which repeatedly showed the reverse association compared to the other markers." (PMID 31088547, 2019). "Reduced macrophage abundance within the tumor core and submucosa was also observed in the mast cell-deficient gp130FF; Cpa3-Cre; Mcl1fl/fl mice and cromolyn-treated gp130FF mice." (PMID 31227713, 2019). "Histamine, closely associated with tryptase, chymase, and carboxypeptidase A3 in MC granules, is also likely released into the extracellular matrix during secretion and exerts proangiogenic properties that promote the formation of tumour blood vessels." (PMID 40981193, 2025). "Tumour-associated MCs accounted for 0.7% of the total pool of immunopositive cells and included both mucosal and connective tissue subpopulations, predominantly of the tryptase + chymase-CPA3-specific protease phenotype." (PMID 40981193, 2025). "Notably, among tumour-associated MCs, the Tryptase+Chymase-CPA3- phenotype prevailed, accounting for more than half of the examined population." (PMID 40981193, 2025). "However, they showed CPA3 positivity, hence indicating that the tumor‐associated MCs in Mcpt6−/− mice were also of CTMC subtype." (PMID 31894627, 2020). "Importantly, mast cell-deficient gp130FF;Cpa3-Cre; Mcl1fl/fl mice had significantly reduced tumor mass and tumor number compared to their mast cell-proficient controls, and this observation coincided with reduced angiogenic vessel density in the tumors of gp130FF; Cpa3-Cre; Mcl1fl/fl mice." (PMID 31227713, 2019). "In contrast, DAPK1, ASPG, and CPA3 were more highly expressed in normal tissues than in tumor tissues." (PMID 41425595, 2025). "Tryptase, chymase, and carboxypeptidase A3, characterised by selective secretion to targets within the tissue microenvironment, can exert multifaceted effects on tumour development." (PMID 40981193, 2025). "The mRNA and protein level of CPA3 was decreased, while the remaining six gene levels were increased in clinical tumor tissues." (PMID 37583701, 2023). "The CPA3 transcript is highly upregulated and readily detected in human mastocytosis as well as in mast cells infiltrating various human neoplasms, making it a potentially useful biomarker for detecting neoplastic mast cells." (PMID 35237679, 2022). "The interaction of mast cells with tumor cells through tryptase and CPA3 leads to antitumorigenic effects, the mechanisms of which are subject to thorough analysis for further studies." (PMID 36012196, 2022). "The true biological role of CPA3 remains elusive, yet some clues exist linking CPA3 expression to tumor progression." (PMID 34894899, 2022). "(d) Quantitative RT-PCR analysis of Cpa3 transcripts (relative specific for mast cells) and Mcpt8 (relative specific for basophils) in tumour tissue, peri-lesional skin and UT belly skin from WT mice (n = 9)." (PMID 31931959, 2020). "CPA3 was also released from the MCs populating the tumor parenchyma, although the extent of release and uptake into tumor cells was less pronounced." (PMID 31894627, 2020).
tumor (continued). "Akin to our observations genetic observations in gp130FF; c-KitW-sh/W-sh and gp130FF; Cpa3-Cre; Mcl1fl/fl mice, cromolyn treatment of gp130FF mice also reduced macrophage accumulation, tumor angiogenesis and proliferation." (PMID 31227713, 2019). "In line, RT-qPCR revealed the upregulation of MC-specific genes Cd117 and Cpa3 in the tumor tissue." (PMID 38942797, 2024). "However, since mast cells contain several mediators, including tryptase and carboxypeptidase A3, these are also reported to be involved in tumor pathophysiology." (PMID 37175975, 2023). "We noticed that the secretion of tryptase and CPA3 primarily affected tumor cells." (PMID 36012196, 2022). "To see whether CPA3 labeling was comparable to the most commonly used MCT marker c-kit, we performed c-kit and CPA3 immunolabeling in serial sections from 3 tumor samples." (PMID 34894899, 2022). "Since they also expressed CPA3, this indicates that the tumor‐associated MCs are of CTMC rather than MMC subtype." (PMID 31894627, 2020). "In addition, the nuclei of tumor cells contacting with MCs might manifest immunopositivity for tryptase and CPA3." (PMID 36012196, 2022). "Among the 13 ferroptosis- and lipid metabolism–related signature genes, CPA3, DAPK1, and ANGPTL4 exhibited significant positive correlations with most immune checkpoint genes, suggesting that higher expression of these genes may be associated with an immune-activated tumor microenvironment." (PMID 41425595, 2025). "Our findings indicated that CD79A, COL5A1, ERO1A, and GJB2 were significantly overexpressed in tumor tissues compared to normal tissues, while CD101 and CPA3 showed more active expression in normal lung tissues, aligning with our prior analysis." (PMID 39850883, 2024). "The mRNA expression of seven PRAN genes (CCL14, CPA3, CX3CR1, IKZF3, KIF21B, LINC00528, and SLC16A4) showed significant differences between normal and tumor samples in the advanced NSCLC cohort." (PMID 38728242, 2024). "The mRNA expression of seven PRAN genes (CCL14, CPA3, CX3CR1, IKZF3, KIF21B, LINC00528, and SLC16A4) exhibited noticeable difference between normal and tumor in NSCLC." (PMID 38728242, 2024). "CD36 (p value < 2.22e-16), CPA3 (p value < 2.22e-16), NFATC1 (p value = 9.1e-08), and RASGRP2 (p value < 2.22e-16) were highly expressed and SLC2A3 (p value = 0.0015) was lowly expressed in tumor samples." (PMID 32908876, 2020).
cancer (12 papers, 2018 to 2025). A tumor composed of atypical neoplastic, often pleomorphic cells that invade other tissues. "Microarray analysis of cancer tissues from AOM/DSS and AOM/DSS/Ab mice revealed profound differences in the expression of genes associated with mast cells, namely Mctp1, Mctp2, Mctp4, Cma1, Fcer1a, Pla2g2e, and Cpa3." (PMID 37185713, 2023). "The expression of the CPA3 gene is found in mast cells and basophilic leukocytes in patients with an allergic history, and CPA3 is involved in the pathogenesis of cancer and inflammatory diseases of the gastrointestinal tract, and respiratory and cardiovascular systems." (PMID 35736349, 2022). "However, few studies have investigated the role of CPA3 in cancers." (PMID 33441161, 2021). "The hypergeometric distribution showed that in the cancer region, TM4SF1 + cancer cells (Epi-C0) colocalized with the two subtypes of NK cells (T/NK-C4: GNLY and T/NK-C5: NKG7) and mast cells (Mye-C0: TPSB2, Mye-C9: CPA3)." (PMID 36434043, 2022). "The cancer cell subtypes enriched in the cancer region were CRABP2 + cancer cells (Epi-C3), and NK cells (T/NK-C5: NKG7) and mast cells (Mye-C0: TPSB2, Mye-C9: CPA3) were also located in the cancer region." (PMID 36434043, 2022). "Among these proteins, we have identified many differentially abundant proteins identified as having a role in cancer (IFIT1, FASTKD2, PIP4K2B, ARID1B, SLC25A33: overexpressed in TR; CALD1, CPA3, B3GALT5, CD177, RIPK1: overexpressed in NR)." (PMID 29681787, 2018). "We have identified many differentially abundant proteins already identified as having a role in cancer, such as the earlier discussed proteins IFIT1, FASTKD2, PIP4K2B, ARID1B and SLC25A33 (more abundant in TR) or CALD1, CPA3, B3GALT5, CD177 and RIPK1 (more abundant in NR)." (PMID 29681787, 2018). "In another case of MIA (TD6), the cancer cell subtypes enriched in the cancer region, including Clara-like cancer cells (Epi-C1), NK cells (T/NK-C4: GNLY and T/NK-C5: NKG7), Tregs (T/NK-C6: FOXP3) and mast cells (Mye-C0: TPSB2, Mye-C9: CPA3), were also located in the cancer region." (PMID 36434043, 2022).
infection (4 papers, 2014 to 2022). The state of being infected such as from the introduction of a foreign agent such as serum, vaccine, antigenic substance or organism. "Ascaris suum roundworms produce a CPA3 inhibitor to improve parasite survival during infection, and in humans Strongyloides stercoralis infection leads to increased serum CPA3 concentration, suggesting that this enzyme could play a role in S. stercoralis infection." (PMID 34894899, 2022). "In contrast, 43 genes associated with innate immune cells were down-regulated following YFV-DakH1279 infection and only three genes were upregulated (KLRC1, CPA3 and RSAD2)." (PMID 25412185, 2014).
cardiovascular disorder (1 paper, 2024). A disease involving the cardiovascular system. "Among these, CPA3, CAMP, and IL3RA have been found to exhibit strong connections with cardiovascular disorders." (PMID 38753730, 2024).
musculoskeletal disorders (1 paper, 2024). "Altered expression of CPA3, a zinc metalloprotease encoded by the CPA3 gene and released from mast cells, has crucial implications for cardiovascular conditions, musculoskeletal disorders, and immunogenesis." (PMID 38753730, 2024).
CPA3 also shares sentences with these, for which no sentence is quoted: allergies (2 papers); idiopathic pulmonary fibrosis (2); rhinitis (2); viral infection (2); allergic conjunctivitis (1); allergic rhinitis (1); aortic valve disease (1); atherosclerosis (1); gastric cancer (1); glioma (1); hepatocellular carcinoma (1); Insulin resistance (1); male infertility (1); mast cell tumors (1); mesothelioma (1); oral cancer (1); Ovarian tumor (1); prostate carcinoma (1); psoriasis (1); sinusitis (1); Ss (1).